MUC2 (mucin 2, oligomeric mucus/gel-forming)
Diseases named in the same sentence as MUC2 in open-access papers (continued):
Sharing a sentence is not in itself a finding about the gene and the disease.
colitis (continued). "Previous studies have shown that in DSS-treated mice, MUC2 and MUC5AC levels were reduced, which has been confirmed by previous research that DSS-treated mice had lower MUC2 and MUC5AC levels, which resulted in spontaneous colitis development." (PMID 37836386, 2023). "One plausible explanation for this is that microbiota in close contact with the surface epithelium in the absence of a mucus protective barrier in Muc2-/- littermates continually drive colitis-inhibiting Fcgbp expression." (PMID 37359538, 2023). "MUC2, the major mucin secreted in the intestine, plays an important barrier function, and mice lacking MUC2 develop spontaneous colitis." (PMID 36904145, 2023). "In this study, we identified a subpopulation of COX-expressing MSCs that promote intestinal organoid swelling via PGE2 secretion to activate CFTR, support the Muc2 expression of intestinal epithelium, and confer the epithelium resistance to injury in the DSS-induced colitis model." (PMID 37574502, 2023). "Our previous study found that the mucus layer got thicker and the expressions of mucin MUC2 and TJs (e.g., Claudin1 and ZO-1) were enhanced after supplementation with LBP-3 (arabinogalactan type) in DSS-induced colitis, thereby improving the intestinal barrier function." (PMID 37430929, 2022). "Overall, our data demonstrate that absence of IEC AMPK during colitis induction impairs the goblet cell number, with concomitant decreased Muc2 expression." (PMID 35203241, 2022). "Previous studies have reported that Muc2 expression was lowered in IBDs, and that a lack of Muc2 led to spontaneous colitis." (PMID 35883875, 2022). "Notably, experimental colitis reduced the mRNA expression of KLF4, MUC2 and ZO-1in their experiment." (PMID 36685588, 2022). "In addition, the administration of loganin and morroniside as the physiological components of C. fructus prevented epithelial barrier injury by increasing the expression of Muc2, ZO-1, claudin-3, occludin, and E-cadherin in DSS-induced colitis." (PMID 36613533, 2022). "PSG significantly reduced the colonic inflammation by reversing the levels of myeloperoxidase, diamine oxidase activity, iNOS, and COX2 and strengthened the intestinal barrier by increasing the expressions of ZO1, occludin, and MUC2 of IBD mice." (PMID 36017235, 2022). "Both missense mutations in the muc2 gene or total lack of intestinal mucin (muc2 KO) in mouse leads to mucosal friability, spontaneous wound formation in mucosa, and development of colitis." (PMID 33814980, 2021). "The generation of Muc2 knockout mice (Muc2−/−) provided direct evidence that a lack of this main mucus layer component results in the development of spontaneous CRC and colitis." (PMID 33557139, 2021). "The percentage of MUC2+ goblet cells was comparable in WT and Prkar2a−/− mice at the steady state, while during DSS-induced colitis, the number of MUC2+ goblet cells in Prkar2a−/− mice was higher than that in WT mice, suggesting a lower goblet cell loss in Prkar2a−/− mice during colon inflammation." (PMID 34349238, 2021). "MUC2 plays an essential role in epithelial protection, as mice without the Muc2 gene spontaneously develop severe colitis and inflammation-stimulated colon cancer." (PMID 34768787, 2021). "Broken mucus layers resulting from a lack of Muc-2 mucin result in increased intestinal permeability, and they are more likely to develop spontaneous colitis." (PMID 32276396, 2020). "In this study, the LPF and SPFC restored the intestinal goblet cell number accompanying with the increase of MUC2 production that was damaged by DSS and reduced the gene expression of inflammatory cytokines, which indicates that the LPF and SPFC improved colitis." (PMID 32218552, 2020). "In the small and large intestine, the secreted mucus is predominantly composed of MUC2, which forms a considerable chemical barrier to enteric commensals and pathogens so that absence of the secreted MUC2 leads to colitis." (PMID 32182669, 2020).
colitis (continued). "The mucin structure is markedly altered in colitis mouse models, and transgenic mice lacking Muc2 gene developed colitis spontaneously." (PMID 31930146, 2019). "Lack of MUC2 reportedly leads to the development of spontaneous colitis characterized by mucosal thickening and superficial erosions." (PMID 30984791, 2019). "An increase in Muc-2 and TFF3 expression could contribute to protection and enhanced tissue repair in colitis, resulting in improved intestinal histological scores and improved clinical performance observed in these two groups." (PMID 30873029, 2019). "The same authors reported that mice lacking MUC2 showed severe damage against dextran sodium sulfate- (DSS-) induced experimental colitis." (PMID 30984791, 2019). "Also, the expression for cytokine-1 signaling suppressor (SOCs-1) and mucin 2 (MUC-2) intestinal barrier protein showed up-regulation (p < 0.01) compared to DNBS control, revealing tissue recovery after colitis induction by means of these treatments." (PMID 30545135, 2018). "Spontaneous colitis has also been observed without colitis induction, which emphasizes the importance of MUC2 for an intestinal barrier function." (PMID 30002285, 2018). "In addition, we observed that mice with DSS-induced colitis had decreased levels of MUC1 and MUC2 at the mRNA level." (PMID 30393231, 2018). "For example, mice with an impaired mucus layer, as found in mice lacking the MUC2 mucin, develop colitis." (PMID 28898292, 2017). "For example, mice lacking Muc2 and secreted mucus develop colitis but no pathology in the ileum due to the lower abundance of bacteria in the small intestine and induction of the IL-22 pathway of genes regulating barrier function and innate defences." (PMID 26843130, 2016). "In contrast, the intestinal environment in Muc2-/- mice seems to negatively impact the ability of P1 DCs to induce OT-II proliferation regardless of ongoing colitis." (PMID 26121642, 2015). "The lower colonic Muc2 and Tff3 mRNA expressions observed in the DSS-Gln group were consistent with the histological findings that damage to the colonic mucosa was less severe in the colitis group with Gln supplementation." (PMID 24416230, 2014). "Furthermore, elimination of core 3-derived O-glycans in mice (C3GnT−/−) induce a reduction in Muc2 protein, resulting in a greater susceptability to DSS induced colitis as well as to colorectal adenocarcinoma." (PMID 23977158, 2013). "Studies in knock-out mice have suggested that deletion of the murine MUC2 orthologue Muc2 results in the onset of “spontaneous” (i.e., not chemically induced) colorectal cancer and colitis." (PMID 21152122, 2010). "Mice that additionally received amantadine showed an increased number of mature MUC2+ goblet cells, which, given that the severity of colitis was not affected, could be due to changes in differentiation." (PMID 41459492, 2025). "Mice lacking the predominant secretory mucin MUC2 develop spontaneous colitis." (PMID 41300441, 2025). "Most notably, AhRΔIEC mice showed impairment of Muc2 at steady-state conditions and were unable to restore Muc2 after I3C treatment in colitis, while there were no significant differential effects on goblet cells or proliferation markers in IECs between AhRΔIEC and WT." (PMID 38397081, 2024). "The elevated protein levels of MUC2, ZO-1, and occludin were further confirmed using Western blot, suggesting that ZW3 could improve the physical structure of the intestinal barrier during colitis." (PMID 38203732, 2024). "Several studies showed that mice lacking the Mucin 2 gene (MUC2), a glycoprotein produced by GCs that strengthens the gut barrier integrity, were more susceptible to colitis since pathobionts could easily translocate through the intestinal barrier." (PMID 37299452, 2023).
colitis (continued). "Muc2, serving as a primary barrier between the gut microbiome and the intestinal epithelium, plays a crucial role in maintaining gut homeostasis and Muc2−/− mice develop severe colitis due to the absence of protective mucous layers." (PMID 37322488, 2023). "In the current work, the use of QT-NPs after induction of colitis played a significant role in the regulation of gene expression related to tight-junction proteins including occludin, MUC-2 and JAM, unlike the DSS-induced colitic non-treated group, which exhibited downregulation of those genes." (PMID 35884960, 2022). "Therefore, in our study, a large number of in vivo and in vitro experiments have been demonstrated that melatonin-mediated MT2 inhibits aeromonas-goblet cell interactions to restore the level of MUC2 production via the LPS/TLR4/MyD88/GSK-3β/ROS/NF-κB loop, further improving colitis in SD mice." (PMID 35355860, 2022). "Despite the reduced goblet cell numbers and Muc2 expression in the proximal colon and increased Mucispirillum Schaedleri abundance in mice lacking epithelial Gpr35, we did not observe any signs of spontaneous colitis in these animals." (PMID 35264769, 2022). "The SPFC and LPF treatments increased the gene and protein expression levels of MUC2 in the rats with DSS-induced colitis compared with the expression levels in the negative control rats, and immunohistochemistry (IHC) showed an increase of the intestinal MUC2 level." (PMID 32218552, 2020). "n‐3 polyunsaturated fatty acids attenuate induced colitis by reducing inducible nitric oxide synthase (iNOS), cyclooxygenase‐2 (COX‐2), IL‐6, and LTB4 as well as regulating tight junction proteins (occludin, claudin‐1) and colonic mRNA levels of trefoil factor 3 (TFF3) and mucin 2 (MUC2)." (PMID 32410383, 2020). "Thus, in this study the decrease in expression of MUC-2 in colitis patients did not involve an increase in inflammation and changes in the level of gene transcription." (PMID 31198858, 2019). "Indeed, Muc2-/- mice lacking a mucus layer develop spontaneous colitis and colorectal cancer demonstrating that Muc2 production impacts intestinal physiology." (PMID 25932952, 2015). "Colonic epithelial cell-specific knockdown of the FASN gene significantly inhibits Mucin 2 (MUC2) palmitoylation, leading to impaired mucus secretion, abnormal intestinal barrier permeability, and flora-immunity imbalance, which eventually may induce colitis and systemic inflammatory response." (PMID 40959086, 2025). "Thus, mice lacking claudin 7, Hnf4a, and Muc2 all develop spontaneous colitis." (PMID 28707083, 2017). "In knockout mice for the mucin 2 gene (Muc2−/−), the mucus layer is absent and spontaneous colitis develops, while in heterozygous Muc2+/− mice, DSS-induced colitis is significantly more severe than in wild-type animals." (PMID 40863977, 2025). "In wound healing assays and an animal model of colitis, cytoplasmic FCGBP not bound to MUC2 played an endogenous role in wound healing to maintain epithelial barrier function." (PMID 37359538, 2023). "In contrast to this distinct protective role of MUC2, not all mucins have shown to have protective functions in a DSS-induced colitis model." (PMID 33013869, 2020).
colon carcinoma (113 papers, 1993 to 2025). "Aside from the alteration in the mucin glycosylation, the downregulation of MUC2 is also associated with metastasis and poor prognosis in colon cancer." (PMID 40699805, 2025). "Muc2 is a mucin secreted from the ileum and colon, and its deficiency is associated with disruption of epithelial homeostasis and the development of colon cancer." (PMID 41009619, 2025). "Studies on the immunohistochemistry of colon cancer also revealed that the low expression of MUC2 is associated with colon tumor and less favorable disease outcome, and lack of expression of MUC5AC and MUC6 were associated with worsened stages of CRC." (PMID 40699805, 2025). "They evaluated 210 cases of stage II colon cancer and found that the complete loss of MUC2 expression resulted in a hazard ratio of 3.32 (95% CI 1.20–9.20)." (PMID 36900282, 2023). "TRPM4 encodes a calcium-activated ion channel, which, in a human colonic cancer cell line, controls calcium-mediated secretion of MUC2, a major component of intestinal mucus barrier." (PMID 35158942, 2022). "Colonic carcinomas with MUC2-positive and MUC5AC-negative were increased the risk of the nodal metastasis, leading to a poor prognosis." (PMID 33452648, 2021). "Our results imply that MUC2 downregulation is associated with increased expression of the tumor-associated antigens CEACAM5/6 in colon cancer." (PMID 28725043, 2017). "Downregulation of Mucin 2 (MUC2) expression is associated with early carcinogenesis events in colon cancer." (PMID 28725043, 2017). "Similarly, in the case of colon cancer, loss of MUC2 and MUC4 and gain of MUC5AC and MUC16 expression have been reported temporally with oncogenic progression." (PMID 36980526, 2023). "Exploring the phosphorylation of CREB and STAT3 in relation to MUC2 might reveal associations between MUC2 and IL-6 in colon cancer." (PMID 28725043, 2017). "MUC2 encodes a secreted gel-forming mucin and often, its expression is reduced in colorectal adenocarcinoma, whereas expression is unaltered in mucinous carcinomas, a distinct subtype of colon cancer associated with microsatellite instability." (PMID 18000536, 2007). "The increased secretion of IL-6 by MUC2-knockdown tumor cells and enhanced tumor growth observed in the present study suggest that the protective mechanisms of MUC2 in colon cancer may be associated with its effects on suppressing the IL-6/STAT3 signaling pathway." (PMID 25322805, 2014). "Some studies demonstrated that MUC2 acted as a tumor suppressive genes, MUC2 mRNA levels was significantly decreased in the colon cancer compared with the control group (decreased by 30%, respectively)." (PMID 40859234, 2025). "(K–L) Immunohistochemistry (K) and quantification (L) of MUC2+ cells in colon tumors of 5-month-old ApcMin/+ (n=6) and Ctnnb1Δi.enh;ApcMin/+ (n=6) mice." (PMID 39320349, 2024). "where they demonstrated a downregulation of MUC2 production by colon cancer cells due to rIL-6 or macrophage-derived IL-6 treatment in a STAT3-dependent manner." (PMID 39170608, 2024). "Only the Amuc_1434 DUF6268 domain-containing protein of A. muciniphila is able to promote adhesion to the LS174T (colon cancer) cell line, which expresses high levels of MUC2, demonstrating the ability of this bacterium to bind MUC2 in the mouse colon." (PMID 39564479, 2024). "MUC2 is an epithelial mucin expressed in intestinal goblet cells, which can also show positive staining in colon carcinomas." (PMID 36001283, 2023). "Ceacam5, Klk6, Slc35d3, Postn, and Muc2 mRNA analysis improves the detection of tumor cells in the lymph nodes of colon cancer patients." (PMID 37996411, 2023). "The results in the human colonic cancer goblet cell line (HT-29-18N2) showed that TRPM4 protein controls calcium-mediated secretion of MUC2 and MUC5AC in conjunction with a Na+/Ca2+ exchanger NCX." (PMID 35158942, 2022).
colon carcinoma (continued). "MUC2 was purified from the LS174T colon cancer cell line, labeled with a fluorophore via N-hydroxysuccinimide chemistry, and incubated with varying concentrations of AM0627 overnight at 37 °C." (PMID 35405095, 2022). "MUC2 is important in maintaining the integrity of intestinal barrier, as MUC2 knock-out mice spontaneously developed inflammation and colon cancer." (PMID 34386004, 2021). "In addition, a previous study has reported an increase in the incidence of colon tumors in MUC2-knockout mice, which is similar to the inflammatory response in mice with adenomatous polyposis coli gene mutation, indicating that the loss of MUC2 expression is related to the inflammatory response." (PMID 33996974, 2021). "In humans, high expression of MUC2 in colon cancer is attributed to better prognosis and less severe tumors." (PMID 34849464, 2021). "Another report demonstrated that DCA-induced MUC2 protein expression of human colon carcinoma cells leads to mucin production which is a carbon source of A. muciniphila." (PMID 33159542, 2020). "A secondary bile acid, deoxycholic acid, induces the transcription of MUC2 in colon cancer cell line HM3, which is inhibited by the JNK-mediated pathway." (PMID 32283838, 2020). "Decreased MUC2 expression allows bacteria to contact the epithelial surface, triggering inflammatory bowel disease, which can lead to colon cancer." (PMID 31933627, 2019). "F. nucleatum attaches to cancer tissues through the interaction of Fusobacterium lectin Fap2 with tumour-specific surface Gal-Gal NAc, and this interaction leads to MUC2 and TNFα expression in the colon cancer cells." (PMID 29317709, 2018). "As a next step and in order to prove human relevance, we analysed two human colon cancer cell lines well known to have different MUC2 secretion levels, namely, LoVo (high MUC2) and Caco-2 (low MUC2) cells." (PMID 28779026, 2018). "Using goblet cell‐like LS174T colon carcinoma cells which produce MUC2 glycoproteins, we found that EHEC O157:H7 prototype strains adhered better to this cell line compared to mucus‐deficient Caco‐2 and HT‐29 cells." (PMID 28054754, 2017). "Our previous study demonstrated that the suppression of MUC2 in CT26 colon cancer cells induces IL-6 secretion and plays an important role in tumorigenesis in an animal model." (PMID 28725043, 2017). "MUC2 gene expression was significantly decreased in several types of colon cancer, including AC, CRC, rectal AC, and cecum AC." (PMID 28725043, 2017). "In conclusion, this study is the first to examine the interaction between MUC2 and IL-6 protein expression in human colon cancer." (PMID 28725043, 2017). "Patients with a lower level of MUC2 expression had a trend of higher IL-6 expression in colon cancer cells and specifically higher infiltration by immune cells (P = 0.0446)." (PMID 28725043, 2017). "The relationship between MUC2 and IL-6 gene expression and colon cancer patient prognosis was examined using the PrognoScan database." (PMID 28725043, 2017). "MUC2 plays a role in the progression of colon cancer, and reduced MUC2 protein expression correlates with increased interleukin-6 (IL-6) expression." (PMID 28725043, 2017). "Apart from MUC2, LS174T cells also secrete MUC5AC, which is usually expressed in the stomach but also associated with colon cancer." (PMID 28054754, 2017). "MUC2 suppressed the migration of colon cancer cells in vitro and dramatically diminished liver metastases in vivo." (PMID 28725043, 2017). "We previously demonstrated that MUC2 suppression enhances IL-6 secretion in the colon cancer cell line CT2619." (PMID 28725043, 2017). "To further investigate the interaction between MUC2 and IL-6 in colon cancer, we compared the expression of MUC2 and IL-6 in normal colon and colon cancer tissues using the Oncomine database." (PMID 28725043, 2017). "We first analyzed the MUC2 protein expression in five human colon cancer cell lines (HT-29, LS174T, SW620, Colo205, and LoVo)." (PMID 28725043, 2017).